ROCK2 (Rho associated coiled-coil containing protein kinase 2)
Diseases named in the same sentence as ROCK2 in open-access papers (continued):
Sharing a sentence is not in itself a finding about the gene and the disease.
cardiac hypertrophy (18 papers, 2015 to 2025). "Increased ROCK2 was associated with the pathogenesis of Ang-II-induced cardiac hypertrophy via regulating FHOD3 phosphorylation." (PMID 32685439, 2020). "On the other hand, global hemizygous ROCK2 deficient and cardiomyocyte-specific ROCK2-deficient mice were found to be resistant to pressure overload-induced cardiac hypertrophy and fibrosis formation, supporting that ROCK2 is important in mediating the cardiac hypertrophic response." (PMID 35043239, 2022). "Furthermore, ROCK2 in cardiac fibroblasts is necessary to cause cardiac hypertrophy and fibrosis." (PMID 30562953, 2018). "It has been reported that ROCK2 is connected to diverse cardiovascular diseases, including atherosclerosis, hypertension, cardiac hypertrophy, and ischemic stroke." (PMID 35971637, 2022). "Recent studies have shown that the ROCK2 pathway in fibroblasts is critically important for mediating AngII-stimulated cardiac hypertrophy and fibrosis." (PMID 34244467, 2021). "This is an interesting finding since ROCK2 has been deemed essential for the development of cardiac hypertrophy." (PMID 32189431, 2020). "As ROS stimulates myocardial hypertrophy, matrix remodeling, and cellular dysfunction, Rho-kinase (especially ROCK2) and CyPA promote ROS production, as well as cardiac hypertrophy and failure in a synergistic manner." (PMID 30562953, 2018). "In contrast, ROCK2–/– mice showed decreased cardiac hypertrophy compared with littermate controls after pressure-overload." (PMID 30562953, 2018). "With respect to the heart, findings in isoform-specific knockout mice argue for a role of ROCK1 and ROCK2 in the pathogenesis of cardiac fibrosis and cardiac hypertrophy, respectively." (PMID 26635606, 2015). "In contrast to the proposed role of ROCK1 in cardiac fibrosis, ROCK2 was shown to be an important player in cardiac hypertrophy." (PMID 26635606, 2015). "Additionally, fibroblast-specific ROCK-2 was reported to promote cardiac hypertrophy, fibrosis, and diastolic dysfunction due to upregulation of the profibrotic gene (CTGF) and promyofibroblast differentiation (α-SMA) genes." (PMID 31814833, 2019). "Furthermore, GLP-1 agonist liraglutide has been shown to ameliorate myocardial hypertrophy in hypertensive rats, potentially through ROCK2 decrease, as in H9C2 cells, GLP-1 decreased ROCK2, and Y27632 further decreased AngII effects on hypertrophic gene ANP expression when combined with GLP-1." (PMID 40182055, 2025). "Interestingly, it seems that ROCK1 may promote cardiac fibrosis, whereas ROCK2 may induce cardiac hypertrophy." (PMID 35784531, 2022). "Of note, the mice used in this study were infused with Ang II rather than having diabetes induced, but because DCM is characterized by high Ang II concentration and a similar hypertrophic phenotype, we can speculate that ROCK2 promotes cardiac hypertrophy in mice." (PMID 35784531, 2022). "Thus, Rho-kinase, especially ROCK2, and CyPA may promote ROS production, as well as cardiac hypertrophy and failure in a synergistic manner." (PMID 30562953, 2018). "However, cardiomyocyte-specific ROCK2-deficient mice showed a slight, but not dramatic improvement in cardiac hypertrophy and fibrosis under pressure-overload." (PMID 30562953, 2018). "Since ROCK2 promotes cardiac hypertrophy and ROCK1 is cardioprotective, celastrol ameliorates pathological cardiac remodelling and postcapillary PH by blocking the corresponding augmentation of detrimental ROCK2 signalling." (PMID 36009315, 2022). "Other studies using ROCK1 and ROCK2 KO mice and ROCK inhibitors in various animal models indicate the involvement of ROCK in diabetic vasculopathy, ischemia/reperfusion injury, heart failure, cardiac hypertrophy, and fibrosis." (PMID 29749605, 2018).
cardiac hypertrophy (continued). "Interestingly, in aortic constriction model, the cardiomyocyte‐specific deletion of ROCK2 suppressed the cardiac hypertrophy 78, while the ROCK1 haploinsufficiency did not prevent cardiac hypertrophy but reduced fibrosis under the same condition." (PMID 29749605, 2018).
diabetes (18 papers, 2013 to 2026). "The development of ROCK2-selective inhibitors has opened new avenues for targeted therapy in CKD among people with diabetes." (PMID 41311514, 2026). "Pharmacological studies have shown that ROCK inhibition ameliorates diabetes-induced cardiac dysfunction and a study using heterozygous ROCK2 KO mice demonstrated that ROCK2 phosphorylates ryanodine receptors, impairing cardiac Ca2+ homeostasis." (PMID 39122698, 2024). "We first investigated the renal and glomerular-specific ROCK2 expression in rodent models of diabetes." (PMID 35396346, 2022). "Transmission electron microscopy (TEM) micrographs from PR2KO mice revealed a significant reduction in foot process width and glomerular basement membrane (GBM) thickness in comparison to ROCK2-floxed mice in the setting of diabetes." (PMID 35396346, 2022). "Of note, the selective deletion of ROCK2 in podocytes resulted in significant protection against diabetes-induced albuminuria and renal hypertrophy, without affecting body weight or blood glucose levels." (PMID 35396346, 2022). "In our current study, we identified a signaling pathway for the development of diabetic renal damage and suggest ROCK2 as an essential energy mediator in podocytes, thus advancing our knowledge of the molecular basis of CKD caused by diabetes." (PMID 35396346, 2022). "We found that podocyte Rho associated coiled-coil containing protein kinase 2 (ROCK2) is activated in rodent models and patients with diabetes." (PMID 35396346, 2022). "Cardiomyocytes from diabetic mice develop arrhythmic calcium transients in response to increased [Ca2+] which is attenuated in cardiomyocytes from diabetic ROCK2 mice suggesting that ROCK2 contributes to diabetes-induced impaired cardiac calcium homeostasis." (PMID 32375786, 2020). "In contrast, in similar haploinsufficient ROCK1+/– and ROCK2+/– KO mouse lines a decrease in blood pressure under basal conditions and an attenuation of the diabetes-induced blood pressure increase was observed." (PMID 26635606, 2015). "ROCK2 expression was borderline significantly increased in our diabetic animals, as reported in retinal vessels from rats 2 weeks after inducing diabetes." (PMID 24059472, 2013). "Such an approach could be particularly advantageous in CKD with diabetes, where ROCK2 inhibition might simultaneously alleviate glomerular inflammation and fibrosis while improving sodium homeostasis." (PMID 41311514, 2026). "ROCK2 contributes to diabetes-induced impaired cardiac Ca2+ homoeostasis." (PMID 36775902, 2023). "To investigate whether the deletion of ROCK2 in podocytes rescues some of the key features of CKD in diabetes, we injected STZ, crossed with db/m mice to generate db/db, or challenged mice with HFD." (PMID 35396346, 2022). "Hence, in three different methodologies using pharmacologically, genetically, and diet-induced diabetes, the deletion of ROCK2 prevented podocyte damage, and as a consequence, the glomerular morphology was preserved." (PMID 35396346, 2022). "When the upregulation of podocyte ROCK2 in subjects with diabetes is taken into consideration, targeting this machinery might provide meaningful renal benefits in humans." (PMID 35396346, 2022). "ROCK2 is found to be activated in 3 diabetic models and patients with diabetes." (PMID 35396346, 2022). "We also analyzed the effect of diabetes ROCK-2 distribution in RPE cells." (PMID 28821742, 2017). "This does not exclude that fasudil could have other inhibiting effects through ROCK-2 inhibition in the retina during diabetes." (PMID 28821742, 2017). "Interestingly, reduced ROCK1 expression was more effective in preventing diabetes-induced changes than ROCK2." (PMID 26635606, 2015). "Up-regulation of arginase was reduced in haploinsufficient diabetic ROCK1 and ROCK2 mice, which could explain the attenuation of diabetes-induced vascular endothelial dysfunction and improvement in vascular function during diabetes." (PMID 26635606, 2015).
diabetes (continued). "This suggests that ROCK2 is a critical node in the development of diabetic cardiomyopathy and may be an effective target to improve cardiac function in diabetes." (PMID 24466133, 2014). "As summary, the present data demonstrated that diabetes-induced vascular dysfunction can arise due to either inhibition of eNOS, thereby less endothelial NO-production, either directly or indirectly, in part due to an upregulation of ROCK2 by hyperglycemia." (PMID 23530857, 2013). "We demonstrated that diabetes-induced vascular dysfunction can arise due to either inbition of eNOS, thereby less endothelial NO-production, either directly or indirectly, in part, due to an upregulation of ROCK2 by hyperglycemia." (PMID 23530857, 2013). "When taken into the context of our current data, it is plausible to conclude that the beneficial renal actions of ROCK2 inhibition in diabetes may be due to the re-sensitization of podocytes to insulin signaling or prevention of metabolic stress in association with the recovery of FAO." (PMID 35396346, 2022). "The major findings of this study were that diabetes led to an upregulation in ACE, ROCK1, ROCK2, and omega-hydroxylase proteins and a downregulation in ACE2 protein that was accompanied by abnormal vascular reactivity in the rat CC." (PMID 25309930, 2014). "In order to demonstrate a role of ROCK isoforms in diabetes-induced vascular dysfunction, we first examined the protein levels of ROCK1 and ROCK2 in both endo(−) and endo(+) aortic rings from both groups of rats (respectively)." (PMID 23530857, 2013). "Mice that lacked ROCK2 only in podocytes (PR2KO) were resistant to albuminuria, glomerular fibrosis, and podocyte loss in multiple animal models of diabetes (i.e., streptozotocin injection, db/db, and high-fat diet feeding)." (PMID 35396346, 2022). "We found that Podocin-cre-mediated ROCK2 deletion in podocytes did not lead to any defects in the development or function of the kidney under physiological conditions; however, it alleviated albuminuria and glomerular sclerosis in three animal models of diabetes." (PMID 35396346, 2022). "In our experimental model, ROCK-2 is expressed in RPE and endothelial cells (not shown) but its cellular distribution is not modified by diabetes suggesting that ROCK-2 may be submitted to other diabetic-induced changes, not analyzed in this paper." (PMID 28821742, 2017).
osteosarcoma (18 papers, 2015 to 2025). A usually aggressive malignant bone-forming mesenchymal neoplasm, predominantly affecting adolescents and young adults. "We also confirmed from a clinical perspective that ROCK2 is an independent prognostic factor in patients with osteosarcoma, is associated with worse patient prognosis, and correlates with the Hippo pathway." (PMID 40670295, 2025). "In this study, we found that Rho-associated coiled-coil containing protein kinase 2 (ROCK2) expression increased in osteosarcoma cells after MPPa-PDT treatment." (PMID 40670295, 2025). "Finally, ROCK2 (Rho-associated protein kinase 2) kinase, which is a crucial intracellular mediator regulating osteosarcoma migration, was significantly downmodulated in MG63 OS cells." (PMID 32235738, 2020). "Moreover, ROCK2 expression level has been associated with worse prognosis in osteosarcoma tissues." (PMID 33557274, 2021). "ROCK2 inhibition results in osteosarcoma sensitivity to MPPa-PDT and is accompanied by a decrease in cellular autophagy levels." (PMID 40670295, 2025). "In conclusion, our study establishes a novel mechanism to reverse MPPa-PDT resistance in osteosarcoma by targeting ROCK2-mediated autophagy, providing new targets and research ideas for the clinical treatment of osteosarcoma MPPa-PDT resistance." (PMID 40670295, 2025). "Targeted inhibition of ROCK2 by screening for J059-0149 increases the sensitivity of osteosarcoma to MPPa-PDT." (PMID 40670295, 2025). "Rescue experiments further showed that ROCK2 mediates MPPa-PDT resistance in osteosarcoma by regulating autophagy." (PMID 40670295, 2025). "Mechanistic studies have shown that ROCK2 mediates autophagy in osteosarcoma cells by regulating the Hippo signalling pathway." (PMID 40670295, 2025). "Specifically, ROCK2 affects osteosarcoma progression and TRAIL resistance by modifying O-GlcNAcylation levels through the ubiquitin-mediated protein degradation of OGT." (PMID 39487556, 2024). "ROCK2 promotes osteosarcoma growth and metastasis by modifying the PFKFB3 ubiquitination and degradation." (PMID 36775902, 2023). "ROCK1 and ROCK2 are the negative regulators of the Hippo tumor suppressor pathway, and while activation of the Rho/Rock signal can increase YAP activity in pleural mesothelioma, ROCK2 knockout decreased tumor volume in a mouse model of osteosarcoma." (PMID 33178014, 2020). "In osteosarcoma, transfection of CD99 inhibited tumor metastasis through the suppression of c-Src and Rho-associated, coiled-coil-containing protein kinase 2 (ROCK2) activities." (PMID 29534016, 2018). "All these findings confirmed that up-regulation of MALAT1 promoted pulmonary metastasis of osteosarcoma via the miR-144-3p/ROCK1/ROCK2 pathway in vivo." (PMID 28938647, 2017). "Inhibition of MALAT1 decreased metastasis and proliferation by regulation of ROCK1/ROCK2 via ceRNA of miR-144-3p in osteosarcoma cells in vitro." (PMID 28938647, 2017). "Previous studies including ours reported that ROCK1 and ROCK2 were closely involved in osteosarcoma proliferation and migration/invasion." (PMID 28938647, 2017). "In brief, all the data above confirmed that MALAT1 promoted proliferation/metastasis by promoting ROCK1/ROCK2 via a ceRNA of miR-144-3p in osteosarcoma cells MNNG/HOS." (PMID 28938647, 2017). "Additionally, ROCK2 promoted osteosarcoma growth and metastasis by modulating the ubiquitination and degradation of PFKFB3." (PMID 40615369, 2025). "Furthermore, we detected the ROCK1 and ROCK2 expressions in osteosarcoma cell lines after PD-L2 knockdown." (PMID 30886151, 2019). "Up-regulation of miR-144 could suppress osteosarcoma cells migration and invasion by targeting regulation of rho associated coiled-coil kinase 1 (ROCK1) and rho associated coiled-coil kinase 2 (ROCK2)." (PMID 28938647, 2017).
osteosarcoma (continued). "Lastly, the incorporation assays as well as CCK-8 assays and transwell assays were re-executed to finally determine whether MALAT1 could regulate ROCK1/ROCK2 and their mediated proliferation/metastasis via a ceRNA of miR-144-3p in osteosarcoma cells MNNG/HOS." (PMID 28938647, 2017). "But the function and mechanism it works on in osteosarcoma proliferation and metastasis mediated by Rho associated coiled-coil containing protein kinase 1 (ROCK1) and Rho associated coiled-coil containing protein kinase 2 (ROCK2) remain unclear." (PMID 28938647, 2017). "Of note, ROCK2 promotes YAP activity, whereas ROCK2 deprivation leads to the inhibition of metastatic potential in osteosarcoma cells through modulation of YAP activity." (PMID 35422060, 2022). "In osteosarcoma, exogenous CD99 was shown to inhibit osteosarcoma cell migration through inhibition of Src and Rock2." (PMID 33147457, 2020). "A study in osteosarcoma demonstrated that CD99 exogenous expression inhibits cell migration through inhibition of Src and Rock2." (PMID 33147457, 2020). "Previous study has demonstrated that miR-144 could suppress osteosarcoma growth and metastasis by targeting ROCK1 and ROCK2, so we wondered whether there was a similar “ceRNA” network among MALAT1, ROCK1/ROCK2 and miR-144-3p." (PMID 28938647, 2017). "In summary, the findings of this study based on the ceRNA theory, combining the research foundation of miR-144-3p, ROCK1 and ROCK2, taking MALAT1 as a new point of study, provided new insights into molecular level proliferation reversal and metastasis of osteosarcoma." (PMID 28938647, 2017). "The lncRNA MALAT1 reduces the protein expression levels of RhoA, ROCK1, and ROCK2, indicating that MALAT1 may promote osteosarcoma cell migration by the RhoA/ROCK pathway; then, MALAT1 increases the number of actin stress fibers in osteosarcoma cells." (PMID 29618386, 2018).
Hypertension (15 papers, 2013 to 2026). The presence of chronic increased pressure in the systemic arterial system. "ROCK2 has also been implicated in the pathogenesis of hypertension, since ROCKs play a crucial role in smooth muscle contraction, through phosphorylation of MLC and MLCP." (PMID 24405853, 2014). "Recently, multiple lines of evidence supporting ROCK2 in the pathogenesis of general hypertension, some studies have looked for genetic association between ROCK2 and hypertension and have found positive results." (PMID 23326532, 2013). "However, there is strong evidence that ROCK signaling plays an important role in the pathogenesis of hypertension in humans, especially because it was shown that polymorphisms in the ROCK2 gene are associated with a lower risk of developing hypertension." (PMID 26635606, 2015). "Moreover, there have been reports that single nucleotide polymorphisms (SNPs) and haplotype of ROCK2 gene are associated with genetic susceptibility for general hypertension." (PMID 23326532, 2013). "The results of long-term prospective, designed for the investigation of gene–gene and gene–environment interactions, in different ethnicity subgroups, enrolling precisely defined patients with hypertension, might produce more conclusive claims about the association between ROCK2 and hypertension." (PMID 23326532, 2013). "ROCK-2 inhibitors can impact vascular function and immune modulation and are contraindicated in patients with significant cardiovascular disease, hypertension, or thrombotic disorders." (PMID 40004842, 2025). "So, a significant target ROCK2 was employed for the treatment of numerous cardiovascular diseases i.e., hypercontraction, atherosclerosis, hypertension, and heart failure." (PMID 37972144, 2023). "ROCK2 relate to coronary artery diseases and hypertension as well as it plays vital function in the contraction of smooth muscle cells than ROCK1." (PMID 37972144, 2023). "A recent study has revealed that phosphorylation of ClC-3 by Rho-kinase 2 (ROCK2) is essential for Ang2-mediated vascular remodeling in hypertension." (PMID 35098884, 2022). "ROCK2 signaling was found to be involved in arterial hypertension, atherosclerosis, myocardial hypertrophy and ischemia-reperfusion injury, vascular remodeling and stroke." (PMID 32370294, 2020). "ROCK1 and ROCK2 appear to be widely expressed, with ROCK2 most abundant in smooth muscle and heart, suggesting an important role of this isoform in the pathogenesis of hypertension, atherosclerosis and cardiovascular disease." (PMID 23326532, 2013). "The sodium-retaining actions of ROCK2 could exacerbate volume overload and hypertension, thereby initiating a vicious cycle that accelerates kidney damage." (PMID 41311514, 2026). "Y27632, a selective small inhibitor of both ROCK1 and ROCK2, was combined with apatinib, and its efficacy was evaluated, wherein it can reduce hypertension induced by apatinib treatment in gastric cancer mice and weaken the activation of the RhoA/ROCK pathway by apatinib and a high-salt diet (HSD)." (PMID 35811723, 2022). "Furthermore, a role for ROCK1 has been suggested in hypertension and increased ROCK2 expression has been described in preeclamptic human placentas." (PMID 25611484, 2015). "Consistently, another Chinese population study did not detect the association between ROCK2 polymorphism and hypertension." (PMID 23326532, 2013). "An additional issue we could not dissect was the biological significance of ROCK2 as a regulator of chronic kidney disease due to other causes, such as hypertension, immune dysregulation, and others (e.g. nonproteinuric kidney disease)." (PMID 38565675, 2024).